CLDN2 (claudin 2)
Diseases named in the same sentence as CLDN2 in open-access papers (continued):
Sharing a sentence is not in itself a finding about the gene and the disease.
diabetes (2 papers, 2017 to 2024). "This indicates an intricate association between CLDN2 and the onset and progression of diabetes, indicating that the CLDN2 expression has altered during metabolic stress in the pre-diabetic period." (PMID 38425650, 2024). "It was found that SPL treatment prevented diabetes-induced loss of cldn-5 in GL, and cldn-2 and occldn in PT evaluated by IB." (PMID 28493961, 2017). "Besides, the role of CLDN2 in T1DM nephropathy and its impact on the pancreas have further strengthened the association between CLDN2 and diabetes." (PMID 38425650, 2024). "We established mouse models for both pre-diabetes and diabetes, validating a significant upregulation of CLDN2 expression in both disease models, with higher expression levels in the diabetes group." (PMID 38425650, 2024). "Here, We identified that CLDN2 is a potential biomarkers for early diagnosis of pre-diabetes through bioinformatics." (PMID 38425650, 2024). "Discussion: These results suggest that CLDN2 can serve as a novel biomarker for pre-diabetes, providing a new direction for future research in the prevention of type 2 diabetes." (PMID 38425650, 2024). "Combined with our bioinformatics analysis, we considered that CLDN2 has the potential of a pre-diabetes biomarker." (PMID 38425650, 2024). "To further validate the alterations of CLDN2 in pre-diabetes and T2DM, we initially established the metabolic stress model of mice to create pre-diabetic conditions." (PMID 38425650, 2024). "To validate alterations of CLDN2 in pre-diabetes and T2DM, we assessed the expression levels of CLDN2 in the pancreas of mice." (PMID 38425650, 2024). "Our results confirmed the potential of CLDN2 as a pre-diabetes biomarker and indicated its potential involvement in the pathogenesis of diabetes." (PMID 38425650, 2024). "The serum of volunteers in impaired glucose tolerance (IGT) group and diabetes mellitus (DM) group also showed higher CLDN2 level." (PMID 38425650, 2024). "The identified CLDN2 gene holds promise as a potential biomarker for early diagnosis and prognosis prediction in pre-diabetes." (PMID 38425650, 2024). "In our previous studies, we found that diabetes decreases the expression of cldn-5 in GL and cldn-2 and occldn in PT, and induces the expression of cldn-4 and -8 in DT." (PMID 28493961, 2017). "We previously studied the impact of diabetes on renal cldns expressions, and described that diabetes decreases the expression of cldn-5 in glomeruli (GL), and cldn-2 and occldn in proximal tubules (PT), in an oxidative stress-dependent way." (PMID 28493961, 2017). "In contrast, it was found that diabetes decreased mRNA levels of cldn-2 and that SPL ameliorated this change." (PMID 28493961, 2017). "In the period of diabetes, there is a dramatic increase in CLDN2 expression within the islets." (PMID 38425650, 2024). "However, the exact relationship between CLDN2 and pre-diabetes is unclear." (PMID 38425650, 2024). "The excessive expression of CLDN2 within the islets of STZ mice during diabetes state may function as a protective barrier to prevent further damage to islet cells or play a compensatory regulatory role, such as signaling pathways related to islet cell proliferation." (PMID 38425650, 2024). "Therefore, we believe that assessing CLDN2 levels may valuable in the diagnosis and assessment of pre-diabetes, which is also the clinical significance of this study." (PMID 38425650, 2024). "The role of CLDN2 in IGT and diabetes requires further elucidation, particularly beyond its functions related to barrier and permeability." (PMID 38425650, 2024). "However, although several studies have explored the possible role of CLDN2 in T1DM, the relationship between CLDN2 and diabetes remained unclear." (PMID 38425650, 2024).
endometrioid adenocarcinoma (2 papers, 2013 to 2018). An adenocarcinoma characterized by the presence of malignant glandular epithelial cells resembling endometrial cells. "By evaluating immunohistochemical scores, low claudin-1 and high claudin-2 protein contents were found in hyperplasia and endometrioid adenocarcinoma (type I), whereas in seropapillary adenocarcinoma (type II), high claudin-1 and low claudin-2 levels were detected." (PMID 30061539, 2018).
endometrioid endometrial adenocarcinoma (2 papers, 2022 to 2024). "The leaky-type TJ protein CLDN-2 has been identified as a potential target for cancer therapy in endometrioid endometrial adenocarcinoma." (PMID 38338691, 2024).
esophageal cancer (2 papers, 2017 to 2020). A primary or metastatic malignant neoplasm involving the esophagus. "The most striking difference between gastric and esophageal cancers was CLDN2 expression, both regarding non-cancerous and tumor tissue." (PMID 32630408, 2020).
esophageal squamous cell carcinoma (2 papers, 2017 to 2020). Esophageal squamous cell carcinoma (ESCC) is a type of esophageal carcinoma (EC) that can affect any part of the esophagus, but is usually located in the upper or middle third. "Previously, upregulated claudin-2 immunoreactivity has been reported in esophageal squamous cell carcinoma while data regarding GC are equivocal." (PMID 32630408, 2020). "Claudin-2 was also highly expressed in esophageal squamous cell carcinoma." (PMID 28212604, 2017). "In the current study, we used immunohistochemical methods to investigate the expression of the tight junction protein Claudin-2 in EAC, esophageal precancerous lesions, and esophageal squamous cell carcinoma." (PMID 28212604, 2017).
interstitial cystitis (2 papers, 2019 to 2020). A rare chronic debilitating urogenital disease characterized by urinary frequency, urgency, and pelvic pain. "We found in this study that claudin-2 was increased in the URO-MCP-1 LPS-induced model for interstitial cystitis." (PMID 33095778, 2020).
intestinal infection (2 papers, 2016 to 2022). "In addition to the known effects of EcN on expression of the sealing TJ proteins ZO-1 and claudin-14, downregulation of claudin-2 can contribute to the efficacy of this probiotic in the treatment of intestinal infections and inflammatory diseases." (PMID 28018313, 2016).
metastasis (2 papers, 2022). The spread or migration of cancer cells from one part of the body (where they first appeared) to another. "For example, CLDN2 expression was recently linked to increased incidence of CRC-associated liver metastasis, whereas CXCR4 and CYP24A1 are increasingly recognized as prognostic markers for CRC progression." (PMID 35159043, 2022).
non-small cell lung carcinoma (2 papers, 2017 to 2026). A group of at least three distinct histological types of lung cancer, including non-small cell squamous cell carcinoma, adenocarcinoma, and large cell carcinoma. "Arteannuin B (Art B), a sesquiterpene lactone from Artemisia annua, combats non-small cell lung cancer (NSCLC) chemoresistance by activating a novel miR-194-3p/CLDN2 axis, as identified here through integrated transcriptomic and functional analyses." (PMID 41981457, 2026). "CLDN2 was previously shown to be a good prognostic factor in non-small cell lung cancer." (PMID 29088828, 2017).
renal clear cell carcinoma (2 papers, 2021 to 2022). "Downregulation of CLDN2 expression, due to the induction of cancer promoting factors, promotes loss of cell–cell contact and YAP translocation to cell nucleus leading to the proliferation and the progression of renal clear cell carcinoma." (PMID 36362947, 2022). "However, claudin-2 role in renal clear cell carcinoma (RCC) remains unknown despite its predominant expression in the proximal tubular epithelium (PTE), the site of RCC origin." (PMID 33622361, 2021). "It is reported that CLDN2 co-immunoprecipitated with YAP and a role of YAP-activation in renal clear cell carcinoma has been established." (PMID 36362947, 2022).
renal fibrosis (2 papers, 2020 to 2021). A final common manifestation of a wide variety of chronic kidney diseases characterized by glomerulosclerosis and tubulointerstitial fibrosis. "Our findings are also consistent with recent studies that claudin-2 KO mice demonstrate exacerbated injury when subjected to hypoxia and claudin-2 expression decreases during renal fibrosis." (PMID 33622361, 2021).
sarcoma (2 papers, 2019 to 2025). A usually aggressive malignant neoplasm of the soft tissue or bone. "The same group recently generated a human-rat chimeric monoclonal antibody against claudin-2 and showed that it accumulated in claudin-2 positive sarcoma xenografts." (PMID 31726679, 2019). "However, CLDN1 shows marked downregulation in pheochromocytoma and paraganglioma (PCPG) (log2FC = -4.7), and CLDN2 exhibits even more pronounced downregulation in sarcoma (SARC) (log2FC = -10.2)." (PMID 41461671, 2025).
thyroid cancer (2 papers, 2013 to 2023). "In this study, biological information analysis identified four genes, HSPA6, FLNC, CLDN2, and E2F1 as candidate biomarkers of thyroid cancer." (PMID 37063290, 2023).
type 2 diabetes (2 papers, 2024). "Here, we used the type 2 diabetic rat model to induce DN and show a nephroprotective effect following the stimulation of PPAR-α, which stabilized renal tight junction components claudin-2, claudin-5, and claudin-16." (PMID 39684861, 2024).
vitamin D deficiency (2 papers, 2024 to 2025). A nutritional condition produced by a deficiency of VITAMIN D in the diet, insufficient production of vitamin D in the skin, inadequate absorption of vitamin D from the diet, or abnormal conversion of vitamin D to its bioactive metabolites. "Vitamin D deficiency is associated with reduced expression of the Vitamin D receptor and epithelial barrier proteins E-cadherin and claudin-2, which play an important role in children with CD in correlation with histological manifestations of disease severity." (PMID 38491474, 2024). "Vitamin D deficiency is thought to be associated with decreased expression of the vitamin D receptor and epithelial barrier proteins E-cadherin and claudin-2, which play an important role in children with CeD in correlation with histological indicators of disease severity." (PMID 40837675, 2025).
abortion (1 paper, 2022). the ending of pregnancy by removing a fetus or embryo before it can survive outside the uterus. "We evaluated the expression of claudin-2, claudin-3, and claudin-10 in the uterine samples from IL-22−/− and WT mice after LPS-triggered abortion." (PMID 36091010, 2022).
aging (1 paper, 2022). A developmental process that is a deterioration and loss of function over time. "The results showed that claudin 2 was closely related to SOX9, and both claudin 2 and SOX9 were closely related to the process of skin aging." (PMID 35965621, 2022).
alcoholic steatohepatitis (1 paper, 2017). "Interestingly, decreased levels of tight junction protein Occludin and increased Claudin-2 overwhelmingly show gut leakiness more often associated with IBS, NAFLD and alcoholic steatohepatitis." (PMID 28328972, 2017).
Allergy (1 paper, 2013). An allergy is an immune response or reaction to substances that are usually not harmful. "Our results show that in addition to the tight junction and the cilium, Cldn2 is also localized on the surface of the epithelium of the small intestine with allergy." (PMID 23990874, 2013).
amoebiasis (1 paper, 2017). "Interestingly, claudin-2 allows water release from the intestinal epithelium, which would be reflected as diarrhea symptom of amoebiasis." (PMID 28861400, 2017).
Arthritis (1 paper, 2020). Inflammation of a joint. "Similar results were found at mRNA expression level with downregulation of ZO-1 and occludin before the onset of arthritis, while the expression of ion and water channel-forming TJ proteins claudin-2 and -15 went up." (PMID 32332732, 2020).
Cirrhosis (1 paper, 2022). A chronic disorder of the liver in which liver tissue becomes scarred and is partially replaced by regenerative nodules and fibrotic tissue resulting in loss of liver function. "In decompensated cirrhosis, expression of claudin-2 is significantly increased, suggesting that this is associated with increased permeability." (PMID 35794599, 2022).
diabetic nephropathy (1 paper, 2017). "Nevertheless, we have previously reported that increased natriuresis is an early alteration observed in diabetic nephropathy and that this is due to loss of cldn-2 in proximal tubule." (PMID 28493961, 2017).
enteritis (1 paper, 2021). Inflammation of the small intestine. "Previous studies have shown that the expression of claudin-2 increases in enteritis, while inhibition of claudin-2 permeability has therapeutic effects." (PMID 34712727, 2021).
esophageal (1 paper, 2017). "However, the relationship between Claudin-2 and bile salt receptors in EAC and esophageal precancerous lesions is still unknown." (PMID 28212604, 2017).
fibrosarcoma (1 paper, 2021). A malignant mesenchymal fibroblastic neoplasm affecting the soft tissue and bone. "Furthermore, a human-rat chimeric monoclonal antibody that recognizes the extracellular domains of human and mouse Claudin-2 has been generated and proven to be safely distributed into the liver, kidney, and tumor tissues of mice bearing Claudin-2-expressing fibrosarcoma cells." (PMID 34079064, 2021).
gall bladder disease (1 paper, 2019). "Since claudin-2 is essential for bile formation, it will be interesting to see if claudin-2 polymorphism might also predispose for gall bladder disease and gallstones." (PMID 31726679, 2019).
gallstones (1 paper, 2019). Solid crystalline precipitates in the biliary tract, usually formed in the gallbladder, resulting in the condition of cholelithiasis. "Accordingly, in claudin-2 KO mice, the rate of bile flow was found to be reduced by half, resulting in a significant increase in bile concentration, and gallstones." (PMID 31726679, 2019).
gastrointestinal carcinomas (1 paper, 2022). "In several gastrointestinal disorders, such as IBDs or gastrointestinal carcinomas, the expression of claudin-2 is increased." (PMID 35707009, 2022).
Granuloma (1 paper, 2021). A compact, organized collection of mature mononuclear phagocytes, which may be but is not necessarily accompanied by accessory features such as necrosis. "Furthermore, we also report that epithelioid macrophages and multinucleated giant cells, found within granuloma in CD, express claudin-2." (PMID 34867313, 2021).
heart failure (1 paper, 2022). Inability of the heart to pump blood at an adequate rate to meet tissue metabolic requirements. "The result suggests that allopurinol-induced oxidative stress might decrease urinary osmolality, possibly via the reduction of aquaporin 1 and/or claudin-2 in proximal renal tubule in patients with heart failure, and topiroxostat might have potential advantages of not worsening oxidative stress." (PMID 35077456, 2022).
Hyperglycemia (1 paper, 2024). An increased concentration of glucose in the blood. "MetS-D animals characterized by high hyperglycemia generated a significant reduction in tissue claudin-2 and -15 mRNA expression (P<0.05)." (PMID 38656073, 2024).
Hyperinsulinemia (1 paper, 2020). An increased concentration of insulin in the blood. "The altered microbiome was associated with increased levels of IL6 in the serum, Claudin-2, IL6, and IL1β in the distal intestine with concurrent inflammatory lesions in the liver and hyperinsulinemia." (PMID 32927823, 2020).
intrahepatic cholestasis (1 paper, 2020). A cholestasis characterized by impairment of the bile flow caused by obstruction located in the liver. "Investigating how claudin-2 expression is regulated in hepatic cells has clinical relevance because deficiency of this protein causes intrahepatic cholestasis and increases gall stone formation in mice." (PMID 32154783, 2020).
leiomyosarcoma (1 paper, 2025). An uncommon, aggressive malignant smooth muscle neoplasm, usually occurring in post-menopausal women. "CLDN2, 3, 4, 5, and 7 were expressed on GISTs and leiomyosarcomas." (PMID 40943068, 2025). "In particular, CLDN2 was detected in all entities, whereas CLDN1 expression was shown predominantly in leiomyosarcoma." (PMID 40943068, 2025).
liver cirrhosis (1 paper, 2015). "Additionally, this two excellent case control studies indicated occludin, claudin-1 and claudin-2 as the significant altered tight junction proteins during the liver cirrhosis decompensating process." (PMID 26152281, 2015).
medullary carcinomas (1 paper, 2014). "Only one patient was positive for CLDN1, CLDN2, and CLDN7 expression, and two of three patients with medullary carcinomas were positive for CLDN4 expression." (PMID 25393310, 2014).
mucositis (1 paper, 2022). Mucositis is inflammation and damage of the mucous membranes lining the mouth and other parts of the gastrointestinal (GI) tract. "Biomarkers were also used to assess the level of intestinal permeability as a result of mucositis; such biomarkers include the tight junction molecules ZO-1, occludin, junctional adhesion molecule-A, and Claudin-2, as well as other biomarkers such as diamine oxidase (DAO) and endotoxin." (PMID 36499758, 2022).
Neonatal sepsis (1 paper, 2015). Systemic inflammatory response to infection in newborn babies. "These spikes in urinary claudin-2 did not appear to correlate with other etiologies of neonatal sepsis, medication use, or need for mechanical ventilation." (PMID 26500853, 2015).
papillary adenocarcinoma (1 paper, 2023). A morphologic variant of adenocarcinoma. "In one papillary adenocarcinoma, both LSR and CLDN-2 were highly expressed at the membranes and in the other adenocarcinomas." (PMID 36961882, 2023). "In the present study Immunohistochemistry showed that CLDN-2 expression in all papillary and invasive lung adenocarcinoma tissues was higher than in normal lung tissues, whereas angulin-1/LSR was highly expressed only in one papillary adenocarcinoma and faintly expressed in the other cases." (PMID 36961882, 2023).
renal carcinoma (1 paper, 2021). A carcinoma arising from the epithelium of the renal parenchyma or the renal pelvis. "Claudin-2 immunoreactivity was sharply decreased in the renal carcinoma samples." (PMID 33622361, 2021).
skin aging (1 paper, 2022). The gradual irreversible changes in structure of skin that occur as a result of the passage of time.. "Our results can provide effective evidence that Sox9 and claudin 2 are involved in the process of skin aging." (PMID 35965621, 2022). "In addition, claudin 2 and SOX9 have similar effects on skin aging related factors." (PMID 35965621, 2022).
small fiber neuropathy (1 paper, 2021). "Proteins and mRNA do not always correspond; this, for example, can also be seen for Cldn2 in intestinal ischemia or NTN1 in keratinocytes and immunoreactivity in skin samples from patients with small fiber neuropathy." (PMID 34576252, 2021).
Stroke (1 paper, 2019). Sudden impairment of blood flow to a part of the brain due to occlusion or rupture of an artery to the brain. "Therefore, our data indicate that the expression of claudin-1 and claudin-2 may be a result from TRPM4 suppression after stroke." (PMID 29569041, 2019).
virus infection (1 paper, 2013). "Western blotting showed that virus infection increased the expression of claudin-2, whereas LGG treatment lowered the claudin-2 level after infection." (PMID 23924832, 2013).
Zinc deficiency (1 paper, 2020). A deficiency of the essential metal Zinc; an essential cofactor for many enzymes. "In Caco-2 cells, zinc deficiency leads to the downregulation of OCLN and ZO-1, and zinc supplementation increases TEER and induces expression of CLDN-2, -7 and ZO-1." (PMID 33182652, 2020).